CDX2 (caudal type homeobox 2)
Diseases named in the same sentence as CDX2 in open-access papers (continued):
Sharing a sentence is not in itself a finding about the gene and the disease.
cancer (continued). "At the 0% cut-off, CDX2 expression was significantly correlated with better overall survival (OS) and cancer-specific survival (CSS)." (PMID 35328309, 2022). "These differentially expressed genes included upregulation of 18 cancer-associated genes (COSMIC Cancer gene census), one of which was CDX2, which has been used to define ‘CDX2-high’ ALL." (PMID 35397658, 2022). "Our previous study has found that some transcriptional factors were cancer type specific methylation, including CDX2 and APC genes." (PMID 36461092, 2022). "The expression of CDX2 progressively decreases with the transition from well to poorly differentiated cancer cell lines." (PMID 34885019, 2021). "Emerging evidence suggests the involvement of caudal-related homoeobox transcription factor 2 (CDX2) in tumorigenesis of various cancers." (PMID 33239678, 2021). "CDX2 have emerged as important modulators of cancer aggressiveness and can influence the viability of HCC cells by transcription regulating oncogene CDH17." (PMID 34147074, 2021). "Immunohistochemically, the cancer cells exhibited strong expression of “intestinal” differentiation markers, including CDX2, MUC2, and MUC5AC." (PMID 34487254, 2021). "CDX2 is also expressed in gastric, pancreato-biliary tract carcinomas and in all carcinomas with histological colorectal appearances, such as ovarian mucinous, bladder, sinonasal, enteric subtype of mucinous, and non-mucinous pulmonary adenocarcinomas." (PMID 33504059, 2021). "Both Cdx2 and Notch can serve to suppress CRC, and their loss of expression is associated with higher grade carcinomas in some cases." (PMID 33525395, 2021). "In this study, we explained the anti-cancer effect of miR-365 in gastric precancerous lesions via regulation of the TLR4/IRF3/YAP/CDX2 axis." (PMID 33292210, 2020). "For liver metastasis, we used CDX2 as a marker of cancer cells and arginase as a hepatocyte marker, which showed CDX2 staining surrounded by arginase in control NT shRNA mice." (PMID 32218208, 2020). "In the Hp-GA network, CDX2 has been reported to be a core TF, which played a key role in IM and cancer." (PMID 33282942, 2020). "Cancer cell proliferation, invasion, migration, and metastasis were stimulated when CDX2 and let-7b were depleted or COL11A1 was over-expressed." (PMID 31938021, 2020). "In adult intestines, CDX2 controls the balance between proliferation and differentiation, and its depletion results in dedifferentiation, leading to cancer pathogenesis." (PMID 32814764, 2020). "We did not observe any SNVs in cancer-associated genes (as listed in MSK-HemePACT cancer panel and COSMIC36) from Scl:Cdx2 MPN BM demonstrating that the emergence of secondary mutations was found exclusively in AL." (PMID 32541670, 2020). "Epithelial claudin expression is modulated by Helicobacter pylori infection; therefore, the analyzed cancer cases were divided into CDX2(+) and CDX2(–) cases." (PMID 31040910, 2019). "This review will address how animal models have refined our understanding of the role of Cdx2 in these common human cancers." (PMID 31739541, 2019). "CDX2 expression is maintained if the metaplasia advances to an adenocarcinoma, but expression diminishes as the cancer loses epithelial morphology." (PMID 31739541, 2019). "While the importance of CDX2 in human cancer pathology is indisputable, its functional role has been more difficult to define." (PMID 31739541, 2019). "In our study, we can show that methylation of CDX2 in cancers with the serrated profile have different degrees of hypermethylation that correlate with CDX2 protein in a dose-dependent manner." (PMID 30257705, 2018). "(2017) reported particular prognostic value of CDX2 for stage IV cancers, in accordance with our findings." (PMID 29900672, 2018).
cancer (continued). "In comparison to MMR-proficient/BRAF WT tumors (70.1% CDX2), those with MMR-deficient/BRAFV600E-mutated cancers (29.3% CDX2) have a significantly reduced expression (p < 0.0001)." (PMID 30257705, 2018). "Specifically, samples were considered as CDX2-positive if 50% or more of the cancer cells displayed widespread nuclear CDX2 expression, whereas samples were considered as CDX2-negative if less than 50% of the cancer cells showed nuclear CDX2 expression." (PMID 29682204, 2018). "In the present study, using whole sections of lesions, we aimed to evaluate alterations in CDX2 expression during cancer progression and to assess the impact of chemotherapy on CDX2 expression in primary CRCs and corresponding liver metastases." (PMID 29682204, 2018). "Taken together, this meta-analysis demonstrates the beneficial effects of CDX2 overexpression on the life expectancy and prognosis of cancer patients, except for the European populations." (PMID 29179508, 2017). "CDX2 acts as a biomarker for gastrointestinal cancer and inhibits the proliferation of different types of cancer cells." (PMID 29156556, 2017). "In conclusion, we demonstrated that H. pylori infection leads to increased expression of CDX2 and VIL1 and that TCTP enhances this expression, and these changes were associated with the development of IM and cancer in the gastric mucosa." (PMID 28536478, 2017). "Among those, MED12, CDX2, MLL and MLL3 are cancer census genes, which are found frequently mutated in other cancers (COSMIC)." (PMID 28256603, 2017). "Our pooled results suggest that despite the presence of its carcinogenic role, the anticancer activity of CDX2 has stronger effects on the clinical prognoses of cancer patients." (PMID 29179508, 2017). "In certain cancer cell lines, the p65 and p50 subunits of NF-κB generate opposing effects on CDX2 expression." (PMID 28460480, 2017). "Second, although the total participant sample size exceeded 5000, the number of included studies was insufficient, especially for the analysis of CDX2 expression with the cancer relapse and the chemotherapeutic effects." (PMID 29179508, 2017). "A subset of the tumors arising in each CDX2-CreERT2 Cdx2fl/fl BrafCA mouse had clear evidence of invasion (carcinoma)." (PMID 28072391, 2017). "On the contrary, another study has shown that CDX2 expression was progressively reduced in gastric dysplasia as well as cancer." (PMID 26926447, 2016). "Whole tissue sections from the same low-grade and high-grade budding cancers were immunostained for β-catenin, E-cadherin, CDX2, ZEB1 and ZEB2 and found to exhibit the expected protein phenotype." (PMID 25528769, 2015). "The small cells carcinomas in addition often show positivity of TTF-1 (thyroid transcription factor-1) or less commonly CDX-2 (caudal homeobox 2 protein) in the GI tract." (PMID 25947008, 2015). "Carcinoma tissue CDX2 expression levels were either similar or less than those of adenomatous polyp epithelium." (PMID 25423035, 2014). "CDX2 protein levels were generally similar or increased in epithelium of adenomatous polyps and carcinoma compared to normal colon tissue." (PMID 25423035, 2014). "Of the 45 cases with diffusely expressing Cdx2, 43 were MMR-proficient (95.6% specificity), whereas 7/9 MMR-deficient cancers showed focal expression of Cdx2 (77.8% NPV)." (PMID 24130965, 2013). "Here, we determine the predictive value of Cdx2 expression for MMR-deficiency and investigate changes in expression between primary cancers and matched lymph node metastases." (PMID 24130965, 2013). "Despite this observation, a subgroup of MMR-proficient cancers also shows focal positivity for Cdx2." (PMID 24130965, 2013). "In summary, our results are encouraging because it can prove that this refined IE assay in CDX2 pCTCs detection is rather specific to CRC among the types of cancers that have been tested." (PMID 21364588, 2011).
cancer (continued). "CDX2 has been reported to possess growth-inhibitory as well as growth-promoting functions in cancer cells." (PMID 19781065, 2009). "Cdx2 plays an important regulatory role in the development of intestinal metaplasia in the foregut, and in cancer development in the colon." (PMID 18190713, 2008). "Immunohistochemistry results with intestinal CDX-2 staining were as follows: cancer cells CDX-2 (+), Pax-8 (-), uterine and bilateral adnexa, high-grade adenocarcinoma (originating from the female reproductive system) with extensive necrosis in the right ovary, and 0.1-cm thick cancerous residue." (PMID 41127008, 2025). "Low expression of CDX2 was associated with shorter cancer-specific survival independent of conventional prognostic parameters in both cohorts." (PMID 39998677, 2025). "SOX2 may play a role in inducing HLA class II expression as the group of CDX2-induced cancers with SOX2 maintenance had a slightly higher expression of these immune presenters." (PMID 40149431, 2025). "With our models, we provide evidence that oxaliplatin-resistant cancer cells have low CDX2 expression; display lower expression of both RPS and RCC genes, and are characterized by RESIST-M signature, all of which collectively correlate with clinical resistance to oxaliplatin." (PMID 40664638, 2025). "Additionally, Reg4 expression was up-regulated by caudal type homeobox 2 (CDX2), which further enhanced cancer cell migration and adhesion through the activation of SRY-related high-mobility group box 9 (SOX9) and G-protein-coupled receptor 37 (GPR37)." (PMID 39857608, 2024). "Therefore, strong associations were shown for breast (Apa1, Bsm1, Cdx2, Fok1, and Taq1), colorectal (Apa1, Bsm1, Fok1, and Taq1), prostate (Apa1, Bsm1, Cdx2, Fok1, and Taq1), and skin (Bsm1, Fok1, and Taq1) cancers." (PMID 39335182, 2024). "The SNP in the Cdx2 (Caudal-type homeobox protein 2, which is an intestine-specific transcription factor with a polymorphic binding site in the VDR gene) has been associated with an overall increased risk of cancer." (PMID 39335182, 2024). "In addition, a higher percentage of cancers with CDX2 mRNA induction showed CIN and MSI high status, while association with EBV was rare." (PMID 39768557, 2024). "Therefore, combining CK7 and CDX2 or adding CDX2 to CK7/CK20 allows for a more comprehensive evaluation of the AoV cancer subtype and aids in predicting prognosis." (PMID 38167037, 2024). "SOS1, RASA1, and NF1 mutations were also significantly more often observed in CDX2-suppressed cancers (10.8%, 9.2% and 13.8%, respectively) than in non CDX2-suppressed cancers (1.8%, 1.8%, and 0.9%, Fisher’s exact test p = 0.003, 0.009, and 0.0001, respectively)." (PMID 39452477, 2024). "Thus, our findings here show that Cdx2 has starkly different roles in regulating stem and differentiation programs, and the resulting cancer dependencies, in the proximal compared to distal colon stem cells." (PMID 38360902, 2024). "In contrast, cancers with low CDX2 showed higher SOX2 expression (mean expression z-score relative to all samples = 0.42, Student’s t test p < 0.0001) and significant HNF4A suppression (mean expression z-score relative to all samples = −1.07, Student’s t test p < 0.0001)." (PMID 39768557, 2024). "CDX2 expression is reportedly retained in SSLs but later decreases in serrated pathway‐associated carcinomas;11, 32 thus mechanisms downregulating SATB2 and CDX2 may also differ." (PMID 37036163, 2023). "Poorly differentiated (G3) carcinomas tended to show a loss of CDX2 (27/33 cases) but not of MUC2 and MUC5AC." (PMID 37240039, 2023). "CDX2 can be a useful marker for differentiating between CRCs and malignant tumors of unknown origin and its expression is useful as a predictor for the prognosis of patients with CRCs." (PMID 35328309, 2022). "Interestingly, CDX2 can be expressed in other malignant tumors, such as lung, ovarian, biliary, and urinary bladder carcinomas." (PMID 35328309, 2022).
cancer (continued). "IHC analysis for CDX2 is used as a marker for intestinal differentiation in cancers of unknown origin in clinical diagnosis." (PMID 36277982, 2022). "A comprehensive illustration on spectrum of primary cancer types in CK7(+)/CDX-2(+)/SATB2(+) tumors might assist in primary tumor identification as well." (PMID 36463302, 2022). "In addition to this panel, Melan-A, CDX2, p63, or p40 were added to patients diagnosed with poorly differentiated carcinoma metastasis." (PMID 35308701, 2022). "In our results, CRC and STAD showed the strongest negative associations with immune response for CDX2, but a negative association was identified also for other cancer types." (PMID 34430923, 2021). "Currently, CDX2 is used as an immunohistochemical marker of intestinal epithelium, especially in classifying cancers of an unknown origin." (PMID 34940086, 2021). "Furthermore, the cancer cells exhibited strong expression of “intestinal” differentiation markers, including CDX2, MUC2, and MUC5AC." (PMID 34487254, 2021). "Using the 5 patients with both normal and cancer cells profiled, we estimated the frequency of inactivation of all 56 colon-specific TFs across the 5 patients, which revealed that CDX2 and TRIM31 were inactivated in 80% of the patients, whereas ATOH1, HNF4A, CDX1, and TBX10 were inactivated in 60%." (PMID 33083012, 2020). "Downregulation of YAP resulted in declined CDX2 expression in cancer cells." (PMID 33292210, 2020). "A majority of these cases, with the exception of AC10 with a CDX2 mutation, did not have any additional driver mutations in the matched carcinoma." (PMID 32895052, 2020). "Some of the transcription factors that were specifically expressed in OS-DW cells were ATF6, CDX2, FOSL1, PRDX3, FZD6, MYNN, TRAF1 which are known to regulate pathways implicated in cancers like, Wnt/Hedgehog/Notch signaling, MAPK signaling, Apoptosis and mTOR signaling." (PMID 31690262, 2019). "As the onset of the cancer is tightly controlled under tamoxifen inducible CDX2 Cre, the changing etiology of the disease can be monitored in a regulated fashion which would be helpful in determining the changes at the different time points of disease progression." (PMID 31766149, 2019). "As the metaplasias progresses to carcinoma, CDX2 levels are often reduced." (PMID 31739541, 2019). "Our group has previously shown that a loss of CDX2 is specific for BRAF mutation and for the CIMP-high phenotype and that both MSI and MSS cancers may show loss of CDX2 in this context." (PMID 30257705, 2018). "CDX2 is also a particularly useful biomarker to classify cancers of unknown origin, when used together with other markers in a panel." (PMID 29900672, 2018). "In addition, CDX2 overexpression in cancer patients with TNM IV stage diseases performed a better response to adjuvant chemotherapy with first-line drugs." (PMID 29179508, 2017). "Moreover, our analysis showed that CDX2 overexpression is correlated to better responses to chemotherapy in patients with TNM IV stage cancers." (PMID 29179508, 2017). "CDX2 is a factor that influences cancer cell differentiation, malignancy, and cancer progression." (PMID 27060927, 2016). "However, SOX2 positive cells were found to display several characteristics of cancer stem cells, as well as a decreased expression of the intestinal epithelial marker CDX2." (PMID 27411517, 2016). "The high-grade budding cancer showed a nuclear translocation of β-catenin toward the invasion front, loss of membranous E-cadherin, absence of CDX2, and increased ZEB1 and ZEB2 in stromal cells at the invasion front." (PMID 25528769, 2015). "Notably, CDX2 was identified in this study as a potential classifier gene with significantly elevated mean expression levels in adenomatous polyp and carcinoma compared to normal tissue." (PMID 25423035, 2014).
cancer (continued). "The aim of this study is to determine the predictive value of Cdx2 expression for MMR-deficiency, the association with clinicopathological features and patient survival as well as to investigate changes in Cdx2 expression between primary cancers and matched lymph node metastases." (PMID 24130965, 2013). "Moreover, loss of Cdx2 is a poor prognostic factor, even among patients with MMR-proficient cancers." (PMID 24130965, 2013). "The significance of alteration of CDX2 expression in human cancers remains unclear, and therefore it is important to define the target genes which are downstream of CDX2." (PMID 23133598, 2012). "Targeting mutated receptor tyrosine kinases in CDX2-suppressed cancers may be a feasible therapeutic strategy, although not all alterations discovered are currently matched with effective inhibitors." (PMID 39452477, 2024). "Similarly, a large proportion of cancers exhibited the combined marker phenotype (CK7-/CK20-/CDX2-) not common to classical adenocarcinoma variants." (PMID 37239344, 2023). "Slug is one of the cancer-related transcription factors, which favors cancer progression and metastasis.In turn, ectopic villin expression regulated by CDX2 (Caudal Type Homeobox 2) may be of great importance in the early stages of intestinal metaplasia and gastric cardia tumors." (PMID 33036298, 2020). "We hypothesized that the percentage of the CDX2-negative component in the primary CRC would increase during cancer evolution, based on recent studies showing that the loss of CDX2 expression was associated with worse prognosis." (PMID 29682204, 2018). "However, the relationship between alterations in CDX2 expression during cancer progression and response to chemotherapy remains unclear." (PMID 29682204, 2018). "In our datasets, we observe strong correlation between loss of CDX2 and the CMS1 and CMS4 subtypes, in accordance with the strong association of CDX2 loss with MSI (CMS1) and worse prognosis (CMS4), and loss of differentiation, a hallmark of CDX2 loss in cancer." (PMID 29900672, 2018). "Reduced levels of CDX2 staining which is correlated with MSI, BRAF mutation, and CIMP were also found in the BRAF mutant/MSS cancers, which suggests that epigenetic silencing associated with CIMP and the BRAF mutation may be contributing to downregulation of CDX2." (PMID 30598662, 2018). "The expression level of CDX2 was not statistically associated with cancer relapse." (PMID 29179508, 2017). "Additionally, this result also suggests that chemotherapy may prolong the OS of high-CDX2-level cancer patients with TNM IV stage diseases." (PMID 29179508, 2017). "Additionally, chemotherapeutic resistance is another challenge for therapeutic efficacy and patient prognosis, and our analysis showed that CDX2 overexpression in cancer patients with TNM IV stage diseases had a better response to adjuvant chemotherapy with first-line drugs." (PMID 29179508, 2017). "Furthermore, the induction of an EMT phenotype, which has been linked to the stem‐like and thus undifferentiated state, can be stimulated by TGFβ and could therefore explain both low levels of CDX2 expression and the immature phenotype of these cancer cells." (PMID 27221051, 2016). "Therefore, the impact of CDX2 on survival is probably cancer type specific." (PMID 24489794, 2014). "However, while most adenomatous polyps tested revealed elevated expression of CDX2 compared to matched normal tissue, the carcinoma samples were more variable with some carcinoma having comparable levels with normal tissue that are consequently reduced compared to adenomatous polyp." (PMID 25423035, 2014). "Immunohistochemistry results were as follows: cancer cells Pax-8 (+), P16 (+), CK7 (+), and CDX-2 (-)." (PMID 41127008, 2025).